PLN (phospholamban)
Description:
Reversibly inhibits the activity of ATP2A2/SERCA2 in cardiac sarcoplasmic reticulum by decreasing the apparent affinity of the ATPase for Ca(2+). Binds preferentially to the ATP-bound E1 conformational form of ATP2A2 which predominates at low Ca(2+) concentrations during the diastolic phase of the cardiac cycle (By similarity). Inhibits ATP2A2 Ca(2+) affinity by disrupting its allosteric activation by ATP (By similarity). Modulates the contractility of the heart muscle in response to physiological stimuli via its effects on ATP2A2. Modulates calcium re-uptake during muscle relaxation and plays an important role in calcium homeostasis in the heart muscle. The degree of ATP2A2 inhibition depends on the oligomeric state of PLN. ATP2A2 inhibition is alleviated by PLN phosphorylation (By similarity). Also inhibits the activity of ATP2A3/SERCA3 (By similarity). Controls intracellular Ca(2+) levels in elongated spermatids and may play a role in germ cell differentiation (By similarity). In the thalamic reticular nucleus of the brain, plays a role in the regulation of sleep patterns and executive functioning (By similarity).
Synonyms: PLB; CMD1P; CMH18
Tractability: Small molecule: a structure with a bound ligand is known. Antibody: UniProt predicts a signal peptide or a membrane-spanning region.
Gene: Protein-coding gene on chromosome 6 (118,543,971 to 118,561,716, forward strand). Ensembl gene ENSG00000198523.
Subcellular location: Endoplasmic reticulum membrane; Sarcoplasmic reticulum membrane; Mitochondrion membrane; Membrane
Pathways (Reactome):
Muscle contraction: Ion homeostasis
Transport of small molecules: Ion transport by P-type ATPases
Gene Ontology:
Molecular function: ATPase inhibitor activity; protein binding; transmembrane transporter binding; transporter inhibitor activity; ATPase binding; enzyme inhibitor activity; identical protein binding; protein homodimerization activity
Biological process: negative regulation of ATPase-coupled calcium transmembrane transporter activity; negative regulation of calcium ion import into sarcoplasmic reticulum; negative regulation of calcium ion transport; negative regulation of heart rate; regulation of ATPase-coupled calcium transmembrane transporter activity; regulation of calcium ion transport; regulation of cardiac muscle cell contraction; regulation of cytosolic calcium ion concentration; regulation of heart contraction; acrosome assembly; blood circulation; circadian sleep/wake cycle, sleep; intracellular calcium ion homeostasis; locomotor rhythm; negative regulation of calcium ion import; regulation of cardiac muscle cell membrane potential; regulation of relaxation of cardiac muscle; regulation of the force of heart contraction; relaxation of cardiac muscle; visual learning; calcium ion transport; response to insulin; response to testosterone; response to zinc ion; spermatogenesis
Cellular component: calcium ion-transporting ATPase complex; endoplasmic reticulum membrane; membrane; mitochondrion; phospholamban complex; sarcoplasmic reticulum membrane; endoplasmic reticulum; perinuclear region of cytoplasm; sarcoplasmic reticulum; mitochondrial membrane; protein-containing complex; vesicle
Genetic constraint (gnomAD): Loss-of-function variants: 0 observed, 1.06 expected, observed/expected ratio (o/e) 0, 90% interval 0 to 1.7. That is too few expected variants to judge how well the gene tolerates losing a copy. Missense variants: 6 observed, 3.78 expected, observed/expected ratio (o/e) 1.59, 90% interval 0.78 to 1.94. Synonymous variants: 3 observed, 1.74 expected, observed/expected ratio (o/e) 1.73, 90% interval 0.61 to 1.94.
Gene-disease validity (ClinGen):
ClinGen rates the evidence that PLN causes each of these diseases.
intrinsic cardiomyopathy (autosomal dominant): Definitive. A cardiomyopathy that is due to abnormalities in heart muscle cells.
arrhythmogenic right ventricular cardiomyopathy (autosomal dominant): Moderate.
Homologues: Orthologues: chimpanzee PLN (98% identical), mouse Pln (98% identical), rabbit PLN (98% identical), rat Pln (98% identical), dog PLN (96% identical), guinea pig PLN (96% identical), pig PLN (96% identical), tropical clawed frog pln (77% identical), zebrafish pln2 (67% identical).
Diseases named in the same sentence as PLN in open-access papers:
PLN is named in the same sentence as 110 diseases in open-access papers, as found by Europe PMC text mining. Sharing a sentence is not in itself a finding about the gene and the disease. The quoted sentences say what the papers report.
heart failure (100 papers, 2009 to 2026). Inability of the heart to pump blood at an adequate rate to meet tissue metabolic requirements. "Human carriers of a p.Arg14del (R14del) variant of the phospholamban (PLN) gene face high risk of developing dilated and/or arrhythmogenic cardiomyopathy, progressing to severe heart failure." (PMID 40905134, 2025). "In contrast, by using gene features, our posterior distribution of shet indicates that PLN is strongly constrained, but TBC1D3 is not, consistent with the observation that heterozygous LOFs in PLN cause severe cardiac dilation and heart failure." (PMID 37292653, 2024). "Impairments in the regulation of Ca2+ cycling proteins, including the ryanodine receptor 2 (RyR2) and the sarcoplasmic/endoplasmic reticulum Ca2+ ATPase 2a (SERCA2a)/phospholamban (PLN) complex, are implicated in heart failure." (PMID 39273430, 2024). "In this study, a brother and a sister, carrying the p.Leu39Ter variant in the PLN gene in homozygous state, developed dilated cardiomyopathy and heart failure, requiring cardiac transplantation at ages 16 and 27, respectively." (PMID 39273332, 2024). "Sarcoplasmic reticulum Ca2+ATPase 2a (SERCA2a) and its main regulator, phospholamban (PLN), affect Ca2+ handling in cardiac muscle and have been implicated in heart failure (HF)." (PMID 37579008, 2023). "The reactivation of the fetal gene program and a downregulation of PLN are often associated with and indicative of pathological hypertrophy and heart failure." (PMID 37362441, 2023). "Superinhibitory phospholamban gene mutations manifest in dilated cardiomyopathy, while loss-of-function mutations are also linked to heart failure [14,]." (PMID 36708951, 2023). "SERCA2a-KO mice exhibit inefficient Ca2+ handling, reduced contractile efficiency, and possible heart failure, while mutations in the phospholamban gene have been linked to hereditary cardiomyopathy and arrhythmias." (PMID 35047109, 2022). "Although PLN-deficient mice demonstrated improved cardiac function, PLN loss in humans can result in dilated cardiomyopathy (DCM) or heart failure (HF)." (PMID 35334215, 2022). "Pathogenic variants of the PLN gene have been linked to the development of arrhythmogenic cardiomyopathies and severe heart failure and have been successfully modelled in mice to assess arrhythmia susceptibility and response to standard heart failure therapy." (PMID 35197863, 2022). "Downregulation of SERCA2a and/or upregulation of phospholamban lead to severe impairment of calcium handling and contractile function serving as a hallmark of cardiac remodeling and heart failure." (PMID 34884213, 2021). "PLN variant carriers presented at a significantly older age yet had worse long-term prognosis, with more LV dysfunction and heart failure." (PMID 34926342, 2021). "Specifically, heart failure is associated with reduced SERCA2a gene expression and reduced phospholamban (PLN) phosphorylation." (PMID 33878037, 2021). "Another calcium-handling protein consistently implicated in contributing to heart failure phenotypes is PLN." (PMID 33878037, 2021). "Mutations on PLN result in intracellular calcium disorder, myocardial contraction defect, and eventually heart failure and/or malignant ventricular arrhythmia." (PMID 33020536, 2020). "The p.(Arg14del) pathogenic variant in the PLN gene results in a high risk of developing dilated or arrhythmogenic cardiomyopathy with heart failure." (PMID 32555305, 2020). "In this study, we generated a novel mouse model with the PLN-R14del pathogenic variant, performed detailed phenotyping, and tested the efficacy of established heart failure therapies eplerenone or metoprolol." (PMID 32555305, 2020). "Previous studies have identified three PLN mutations in heart failure patients with inherited cardiomyopathies." (PMID 31325238, 2019). "A different T116G point mutation resulting in PLN-Leu-39-stop (PLN-L39stop) was also discovered in familial cases of heart failure." (PMID 28102477, 2017).
heart failure (continued). "Overexpression of PP1 observed in heart failure was associated with dephosphorylation of PLN, depressed cardiac function, dilated cardiomyopathy, and premature mortality." (PMID 22472319, 2012). "Based on a link between PLN mutations and heart failure in humans, it is found that the alteration of PLN inhibitory function can lead to degenerative cardiomyopathy." (PMID 21525996, 2011). "A similar effect as with our experiments was seen in human heart failure, where reduced PLN phosphorylation with high CamKII activity could be linked to increased calcineurin activity." (PMID 31034488, 2019). "The precise pathophysiological mechanism in PLN p.Arg14del mutation carriers leading to cardiac fibrosis and heart failure remains unknown." (PMID 24732829, 2014). "In this study, our objective was to determine the presence of the -36A>C alteration in PLN gene in a Brazilian population of individuals with HF and to test whether this alteration is associated with heart failure or with a worse prognosis of patients with HF." (PMID 19638213, 2009). "Furthermore, long-term expression of active inhibitor-1 via recombinant adeno-associated virus type 9 gene transfer in rats with pressure-overload induced heart failure improved function and prevented remodeling, associated with increased phosphorylation of phospholamban at Ser16 and Thr17." (PMID 24312496, 2013). "Alterations in PLN‐SERCA2 interaction and expression, seen in heart failure patients, cause impairment in cardiac relaxation and contraction." (PMID 41494989, 2026). "Other notable targets include PLN (phospholamban), involved in calcium handling abnormalities in dilated cardiomyopathy (DCM), and RBM20, a gene associated with RNA splicing defects in heart failure." (PMID 40465697, 2025). "During the development of heart failure, synergistically decreased SERCA2a levels and dephosphorylation of PLN are typically observed, resulting in reduced calcium reuptake and impaired myocardial contractility." (PMID 40536467, 2025). "The phospholamban (PLN) pathogenic gene variant p.Arg14del causes cardiomyopathy, which is characterized by perinuclear PLN protein clustering and can lead to severe heart failure (HF)." (PMID 38334971, 2024). "In disease conditions such as heart failure, dephosphorylated phospholamban leads to depressed calcium cycling and impaired calcium transport." (PMID 37922111, 2024). "The p.Arg14del mutation in the gene coding for phospholamban (PLN) can cause dilated cardiomyopathy (DCM) and arrhythmogenic cardiomyopathy (ACM), often resulting in severe heart failure (HF)." (PMID 38334971, 2024). "In mice, the overexpression of active (constitutively phosphorylated) I-1 increases PLN phosphorylation and cardiac contractility not only in healthy subjects but also prevents hypertrophy and heart failure in mice with transverse-aortic constriction." (PMID 36766777, 2023). "The phospholamban (PLN) mutation R14del, first described in Greek families with DCM and heart failure, was identified in 2012 in a large number of Danish patients with a clinical diagnosis of ACM or DCM, supporting a broader phenotypic spectrum for ACM." (PMID 37189825, 2023). "Explored the use of ASOs targeting phospholamban as a potential therapeutic option for heart failure." (PMID 37663746, 2023). "PLN deletion hiPSCs-CMs had enhanced contractility at day 30, but proceeded to a cardiac failure phenotype at day 60, with decreased contractility, mitochondrial damage, increased ROS production, cellular energy metabolism imbalance, and poor Ca2+ handling." (PMID 35334215, 2022). "This in turn led to the clear observation of the improved heart function at the physiological level in a mouse heart failure model due to the expression of the PLN inhibiting intrabody." (PMID 35641497, 2022). "The reduction of phosphorylated phospholamban is one important factor determining the observed reduction in SR Ca2+ reuptake in the heart failure." (PMID 35047109, 2022).
heart failure (continued). "The dysregulated physical interaction between two intracellular membrane proteins, the sarco/endoplasmic reticulum Ca2+ ATPase and its reversible inhibitor phospholamban, induces heart failure by inhibiting calcium cycling." (PMID 35641497, 2022). "This idea was once considered revolutionary, as in rodent models, adenoviral-delivered interferent RNA against PLN in the heart allowed researchers to cure the heart failure phenotype." (PMID 35324727, 2022). "Jiang and colleagues show that PLN-KO hiPSCs-CMs result in the heart failure phenotype and ranolazine can partially restore Ca2+ handling disorders and cellular energy metabolism, alleviating the PLN knockout phenotype of HF." (PMID 35334215, 2022). "The recessive PLN p.Glu2Ter mutation however, which is known to prevent PLN synthesis, associates to severe DCM and heart failure." (PMID 35699837, 2022). "In several studies of heart failure on animal models and humans, a decrease in phosphorylation of phospholamban and of SERCA2a activity has been observed." (PMID 35047109, 2022). "We selected the imperative heart failure target, PLN, a challenging target for small molecule approaches, as a case study for our strategy." (PMID 35641497, 2022). "The PLN p.Arg14del founder mutation causes DCM and ACM and is associated with an increased risk of malignant ventricular arrhythmia and heart failure." (PMID 34143416, 2022). "Several mutations identified in phospholamban (PLN) have been linked to familial dilated cardiomyopathy (DCM) and heart failure, yet the underlying molecular mechanism remains controversial." (PMID 35297759, 2022). "A recent knock-in mouse model demonstrated severe cardiac remodeling and heart failure when homozygous for PLN R14del." (PMID 34887420, 2021). "PLN p.Arg14del end‐stage heart failure samples revealed perinuclear aggregates positive for ER marker proteins and oxidative stress in comparison with ischemic heart failure and non‐failing donor heart samples." (PMID 33998164, 2021). "In this direction, the subcutaneous injection of palmitate-conjugated ASO against PLN (phospholamban) was already shown to improve cardiac dysfunction in mouse and rat heart-failure models and increase survival." (PMID 34685492, 2021). "Here the authors show that subcutaneous administration of antisense oligonucleotides targeting PLN is an effective strategy in preclinical models of genetic cardiomyopathy and ischemia-driven heart failure." (PMID 34462437, 2021). "In cases of heart failure, however, phosphorylation of PLN is reduced and this is attributed to dysfunctional adrenergic signaling." (PMID 33878037, 2021). "Agents endowed with “PLN antagonism” have been identified and improved cardiac performance in patients with heart failure, a condition also characterized by overwhelming SERCA2a inhibition by PLN." (PMID 34948294, 2021). "Cyclic adenosine monophosphate (cAMP)-dependent phosphorylation of phospholamban has been proposed to be in part responsible for the reduced SERCA activity in human heart failure." (PMID 34299010, 2021). "RNA-seq analysis of the phospholamban (PLN) R9C model of heart failure (HF) showed that like in the SRFHKO model, upregulation of Nmrk2 gene is an early event occurring prior the development of overt DCM and HF." (PMID 33805532, 2021). "Overexpression of PLN and increases in the ratio of PLN relative to SERCA has been implicated in dilated cardiomyopathy, heart failure, and skeletal muscle myopathies." (PMID 33089074, 2020). "During heart failure, the expression of cardiac SERCA2a was downregulated, and the activity of SERCA2a was inhibited by its modulator, phospholamban." (PMID 33149749, 2020). "Heart failure is correlated with insufficient activity of the sarcoplasmic reticulum Ca-pump (SERCA2a), often due to excessive inhibition by phospholamban (PLB), a small transmembrane protein." (PMID 32397211, 2020).